BAX (BCL2 associated X, apoptosis regulator)
Diseases named in the same sentence as BAX in open-access papers (continued):
Sharing a sentence is not in itself a finding about the gene and the disease.
ovarian carcinoma (continued). "According to a study on ovarian cancer cells, there was no significant increase in the drug susceptibility of tumor cells with BAX overexpression." (PMID 38003498, 2023). "In addition, ZMYND10 can upregulate BAX expression, which facilitates the pro-apoptotic pathway, thereby promoting paclitaxel-induced apoptosis in ovarian cancer cells." (PMID 36158689, 2022). "In addition, the inhibitory effect of 8-CPT-cAMP on BAX protein accumulation was similar to that of dobutamine on the IR-treated BRCA1 knock-down ovarian cancer cells." (PMID 35517499, 2022). "The expression ofthe BAX gene after exposure to platinum(II) complex with 3-aminoflavone at 43 °C on Caov-3 cells correlates with the expression after treatment with paclitaxel, which belongs to the gold standard of ovarian cancer treatment." (PMID 32204470, 2020). "The BAX represent a prognosticindicator of the patients with ovarian cancer and combineevaluation of BAX and BCL-2 may provide additional prognosticsignificance." (PMID 31285648, 2019). "In regard to BAX expression, a few studies have addressed the issue of its clinical significance in advanced stage ovarian carcinomas; however, associations with CR or DFS have not been observed." (PMID 12644821, 2003). "We conclude that BAX expression may represent a prognostic indicator for patients with ovarian cancer and that the combined evaluation of BAX and BCL-2 may provide additional prognostic significance." (PMID 11720475, 2001). "HAGLROS is an upregulated lncRNA in ovarian cancer cells; HAGLROS knockdown increases apoptosis rate, upregulates BAX protein expression, and downregulates BCL-2 protein expression via the HAGLROS/miR-26b-5p axis (Zhu and Mei, 2021)." (PMID 39967908, 2025). "Accumulating evidence has revealed that BER exerts potential pro-apoptotic effects by modulating BAX/BCL2 (pro-/anti-apoptotic) expression in multiple cancers, including breast, lung, liver, gastric, colorectal, pancreatic, and ovarian cancers." (PMID 39275269, 2024). "In ovarian cancer, CBL0137 can activate ROS/BAX signalling and promote caspase-3/GSDME-dependent pyroptosis." (PMID 39616223, 2024). "Our previous studies have shown that by also regulating the BAX/BCL2 genes, CAPE can influence the severity of apoptosis in serum ovarian cancer." (PMID 37570782, 2023). "SALL2 binds target genes, BAX, p16, and c-MYC in ovarian cancer through the canonical GC-rich motif." (PMID 36438565, 2022). "It has been reported that overexpression of β-hCG (CGB5 gene) in the ovarian cancer cell lines OVCAR-3 and SKOV-3 showed a remarkable decrease in the expression of BCL2, but increased expression of BAX and BIRC5." (PMID 34941061, 2021). "For example, in combination with cisplatin, TQ demonstrated an increased expression of the pro-apoptotic BAX and decreased anti-apoptotic BCL2 in a ovarian carcinoma (SKOV3) cell line." (PMID 32793594, 2020). "In cell line studies, BCL-2, BAX, as well as novel MEK1 protein levels have strong influence on ovarian cancer response to cisplatin-based chemotherapy." (PMID 12644821, 2003). "The expression of the BCL-2 family proteins, BCL-2, BAX, BCLXLand BAK have been determined in a panel of 12 human ovarian carcinoma cell lines encompassing a wide range in sensitivity to cisplatin." (PMID 10646901, 2000). "In ovarian cancer cell lines SKOV-3 and OVCAR-3, Ex-4 induces apoptosis by modulating NF-κB downstream targets, including matrix metalloproteinase-9 (MMP-9), intercellular adhesion molecule-1(ICAM-1), BAX, Bcl-2, and cyclin D." (PMID 40140925, 2025).
ovarian carcinoma (continued). "ADA has been shown to induce cell death in hepatoma cells by regulating the ratio of BAX and BCL-2, to impede proliferation in ovarian cancer via GOT1 inhibition, and to exert pronounced anti-cancer activity in prostate cancer cells by inducing DNA damage, cell cycle arrest and apoptosis." (PMID 39175546, 2024). "The proliferation of ovarian cancer cells is considerably inhibited by berberine in a dose- and time-dependent way, and apoptosis is induced, probably via downregulation of anti-apoptotic genes survival and BCL-2, and pro-apoptotic gene BAX upregulation." (PMID 36144625, 2022). "Likewise, we identified that β-sitosterol induced late apoptosis via the activation of apoptotic signals, including cleaved caspase 3 and caspase 9, cytochrome C, BAX, and BAK, in human ovarian cancer." (PMID 34679718, 2021). "This study showed that BCL2A1 interacts with neither BAX nor BAK in ovarian cancer cells, consistent with other studies." (PMID 34572804, 2021). "We decreased BCL9 expression in the ovarian CaoV3 serous cancer cell line and ovarian ES-2 clear cancer cell line, which inhibited BCL2 expression and increased the BAX/BCL2 expression ratio, promoted cell apoptosis, and inhibited the proliferation of ovarian cancer cells." (PMID 31827404, 2019). "Despite these findings, significance of BCL-2 or BAX expression in ovarian cancer response to cisplatin-based chemotherapy has not been confirmed by clinical studies." (PMID 12644821, 2003). "ALDH1A1-knockdown induced DNA damage, evidenced by robust induction of γ-H2AX and BAX mediated apoptosis, with significant increases in BRCA1 expression, suggesting ALDH1A1-dependent regulation of cell cycle checkpoints and DNA repair networks in ovarian cancer stem-like cells." (PMID 25216266, 2014). "Studies on ovarian carcinoma cell lines have revealed an association between high BCL-2 levels and resistance to cisplatin, however, contradictory results have been published, too; BAX expression either enhanced or did not influence ovarian carcinoma cell lines sensitivity to cisplatin." (PMID 12644821, 2003). "BCL-2 and BAX, but not MEK1 expressions have predictive value in ovarian cancer patients treated with platinum-based chemotherapy." (PMID 12644821, 2003).
prostate carcinoma (60 papers, 2013 to 2025). A carcinoma that arises from epithelial cells of the prostate gland. "MEG3 has been implicated in upregulating the expression of BAX and caspase 3, as demonstrated in prostate cancer." (PMID 39108882, 2024). "Conversely, the pro-apoptotic effector protein Bcl-2-associated X protein (BAX) is consistently expressed in 100% of prostate cancer samples across all disease stages, indicating that the core machinery for apoptosis remains intact but is actively antagonized by pro-survival proteins." (PMID 41465187, 2025). "Upon incubation with 9F7-F11, we observed BID cleavage and BIM expression also in DU145 prostate cancer cells, which are BAX-deficient but express BAK that could replace BAX to induce caspase-9 activation." (PMID 31443721, 2019). "Analysis of BAX stability in human prostate adenocarcinoma showed that BAX is highly instable and the reduced BAX protein levels was associated with increased Gleason scores of prostate cancer." (PMID 25806049, 2015). "Neem-derived flavonoids and limonoids also inhibit STAT3, BCL-2, and enhance BAX, Caspase-3, and mitochondrial depolarization in hepatocellular and prostate cancers." (PMID 41346617, 2025). "acephala induce apoptosis by increasing the protein expression of BAX and cytochrome c in human prostate cancer." (PMID 36829815, 2023). "Results were a sign of the fact that the synergism between 5-FU and TRAIL completely depends on BAX expression in prostate cancer cell lines." (PMID 33564285, 2021). "BCL-2 proteins have also been implicated in resistance to radiotherapy in prostate cancer, and an elevated BCL-2/BAX ratio is associated with radioresistance." (PMID 35008216, 2021). "A decreased BCL2/BAX ratio, together with increased caspase-3 activity and protein abundance were observed in PC-3, DU-145 and LNCaP prostate cancer cells after using CAPE synergistically with docetaxel and paclitaxel." (PMID 32752091, 2020). "Similar results were observed in LNCaP prostate cancer cells, and AL treatment dose-dependently increased the ratio of BAX and Bcl-2." (PMID 31467577, 2019). "In LNCaP cells, AL treatment increased the ratio of BAX and Bcl-2, indicating induced apoptosis in this prostate cancer cell line." (PMID 31467577, 2019). "In the present study, the expression ratio of BCL2/BAX was found to be significantly greater after Ang1–7 treatment in all prostate cancer cells." (PMID 30361641, 2018). "BAX mRNA expression was increased in this TCGA dataset and BAX protein had increased expression in prostate cancer." (PMID 26683658, 2015). "Additionally, a recent in vitro study has shown evidence that doxycycline, in combination with doxorubicin, induces apoptosis of prostate cancer cells by increasing BAX expression and decreasing Bcl-2." (PMID 39796759, 2025). "Hesperetin also promotes apoptosis in prostate cancer cells by activating BAX and BAD expression." (PMID 38200039, 2024). "Interestingly, EADR induced apoptosis in prostate cancer cells by upregulating BAX and downregulating Bcl-2, leading to the subsequent reduction of MMP and activation of caspase-3." (PMID 38966207, 2024). "Similarly, Res treatment increases cleaved caspase-3 and BAX proteins in gastric, pancreatic, prostate cancer cells, lymphoma, leukemia, and myeloma cells." (PMID 36982788, 2023).
prostate carcinoma (continued). "While TWIST1 has been shown to suppress BAX in prostate cancer cell lines, further work is warranted to explore whether the upregulation of BAX and BCL‐XL in TWIST1 overexpressed CH1‐ and OV17R‐shFZD7 clones is indeed directly induced by TWIST1." (PMID 30548372, 2019). "On the other hand, it was reported that exposure to zinc sulfate in human prostate cancer cells increased intracellular levels of zinc, resulting in increased apoptosis, which could be due to increased levels of BAX or decreased Bcl-2 and survivin expression." (PMID 26338969, 2015). "Thus, BAX expression restores sensitivity of DU145 prostate cancer cells to apoptosis induced by combination treatments." (PMID 24040284, 2013). "Following this, the expression levels of apoptosis-related genes (BAX, Bcl-2), an angiogenesis gene (VEGF-C), a gene associated with progression and development (HIF-1α), genes involved in the EMT pathway (SNAIL and E-Cadherin), and a prostate cancer marker (KLK3) were evaluated using Real-Time PCR." (PMID 40388455, 2025). "The pro-apoptotic pore forming ‘effector’ BAX was detected in all 88 samples, 86 of which contained >25% of positive staining tumor cells, suggesting that the majority of prostate cancers may still have the core machinery to undergo apoptosis if the apoptotic threshold is breached." (PMID 35008216, 2021). "In this context, one study demonstrated that 22Rv1 cells exhibit nearly undetectable BAX protein levels and that blocking Akt, which targets the BCL-2 signaling pathway, sensitizes castration-resistant prostate cancer cells to enzalutamide." (PMID 40126263, 2025). "The inhibition of the PI3K/AKT pathway, combined with the upregulation of the BAX/BCL2 ratio, collectively supports SSA’s pro-apoptotic and anti-tumor mechanisms, providing mechanistic evidence for its multi-targeted effects in prostate cancer treatment." (PMID 39995416, 2025). "In this research, HLT-101 induced apoptosis in prostate cancer cells by downregulating the expression of BCL-2, an apoptosis inhibitor, and up-regulating BAX, a pro-apoptotic factor." (PMID 37994101, 2024). "We found that EXO1 promoted BCL2, CDC25, and PCNA and inhibited BAX expression, and further experiments showed that EXO1 inhibited apoptosis in prostate cancer cells." (PMID 38279172, 2024). "In the case of prostate cancer, apigenin decreased Bcl-2 and Bcl-xL and increased BAX in PC-3 and DU145 human prostate cancer cells." (PMID 36142874, 2022). "In this regard, the present work aimed to fabricate bismuth oxide nanoparticle functionalized with glutamine and conjugated with TSC and to characterize its effect on prostate cancer cells and expression of CASP8, BAX, and Bcl-2 genes." (PMID 36482061, 2022).
prostate carcinoma (continued). "The overexpression of CXCL3 and its receptor CXCR2 promoted the proliferation and migration of cancer cells by regulating the expression of genes, including ERK, BAX, TP73, and NDRG3, which enhance the oncogenic potential of prostate cancer." (PMID 30686982, 2018). "In LNCaP-104-R1, which are castration-resistant prostate cancer cells that express mutant AR, AR signaling has been suggested to promote ultraviolet or STS-induced apoptosis via BAX protein translocation from the cytoplasm to mitochondria." (PMID 27203692, 2016). "In future work, we will integrate elements downstream of BAD, such as BclXL, BAX and BAK, to investigate a more detailed mechanism related to stress interactions in prostate cancer." (PMID 24339759, 2013). "Additionally, results of the study conducted on twenty-six men with newly diagnosed prostate cancer demonstrated that lycopene might decrease the growth of prostate cancer; however, no significant changes were observed in the expression of markers of apoptosis, Bcl-2, and BAX." (PMID 32859058, 2020). "In prostate cancer, BCL2/BAX ratio is involved in modulation of radiosensitivity." (PMID 30537994, 2018). "Decreased BAX (BCL2 associated X, apoptosis regulator) expression and increased BCL2 (BCL2, apoptosis regulator) expression were observed in all prostate cancer cells (date not shown)." (PMID 30361641, 2018). "In prostate carcinoma cells, an increase in the expression of only four pro-apoptotic genes was observed: p-53-dependent proteins BIM and PUMA, but not BAK and BAX." (PMID 34360564, 2021). "The expression of both pro-apoptotic (BAX,BIK, and BAD) and anti-apoptotic genes(MCL-1 and BCL-XL) was not affected byBAP1-knockdown in prostate cancer cells." (PMID 32422649, 2020). "Interestingly, CDKN1A and BAX were upregulated by TSPX-overexpression in LNCaP cells, but not in TSPX-high clinical prostate cancer samples." (PMID 30863497, 2019).